ISG15 (ISG15 ubiquitin like modifier)
Diseases named in the same sentence as ISG15 in open-access papers (continued):
Sharing a sentence is not in itself a finding about the gene and the disease.
cancer (continued). "In transformed cells, ISG15 overexpression has been detected in several cancer settings and has been linked to tumourigenesis." (PMID 33203188, 2020). "Several studies have indicated that aberration of cell signaling in the ISG15 pathway perturbates ISG15 regulation and causes malignant transformation of various human cancers." (PMID 27626177, 2016). "ISG15 is associated with poor prognosis and it is implicated in cytoskeleton disruption and cancer cell migration." (PMID 27659523, 2016). "Furthermore, ISG15 has also been implicated in cancers such as breast, pancreas, and ovary, where it controls various pathways, including autophagy, exosome secretion, DNA replication stress response, and immune regulation." (PMID 38781019, 2024). "Thus, ISG15 clearly has double-edged functions in malignant cancers, and proper consideration must be given to assessing risk-benefit prior to administering ISG15-targeted cancer therapy to cancer patients when available." (PMID 36771004, 2023). "Interestingly, ISG15 is emerging as an important oncoprotein with a potential diagnostic signature and therapeutic target for several cancers in recent years." (PMID 36831577, 2023). "Thus, ISG15/ISGylation can be over- or down-regulated depending on the type of cancer, and the identification of ISGylated proteins will help in understanding the novel molecular pathways associated with ISG15." (PMID 37711589, 2023). "However, ISG15 is overexpressed in many cancers, and in HCC, ISG15 has been implicated to promote tumorigenesis and metastasis by stabilizing the antiapoptotic protein Survivin." (PMID 37686559, 2023). "An emerging body of evidence reveals that the ISG15 pathway, an antagonist of the ubiquitin pathway, is aberrantly elevated in various human malignancies, implicating its potential role underlying the observed defects in protein degradation in cancer." (PMID 35159348, 2022). "Furthermore, dysregulation of ISG15 and ISGylation is directly or indirectly linked to the pathogenesis of cancer." (PMID 36319753, 2022). "In addition, ISG15 and ISGylation have been associated with cancer stem cell (CSC) maintenance and behaviour, which can be translated into poor prognosis in patients." (PMID 35864381, 2022). "In a proportional hazards, multivariate analysis with cytoreduction status and age adopted as covariates, low ISG15 expression by cancer cells was associated with a poorer overall survival (HR 2.265, 95% CI:1.5–3.43, p < 0.001), and progression-free survival (HR 1.909, 95% CI:1.28–2.84, p = 0.001)." (PMID 30469497, 2018). "The expression of ISG15 and ISG15-mediated conjugation has been implicated in a wide range of human tumors and cancer cell lines, but the roles of ISG15 in tumorigenesis and responses to anticancer treatments remain largely unknown." (PMID 27626310, 2016). "Upregulation of ISG15 activity has been associated with several cancers." (PMID 23826213, 2013). "This could implicate a possible association between ISG15 upregulation and enhanced proliferation or invasiveness of cancer cells." (PMID 18627608, 2008). "Moreover, some cancer therapies, such as chemotherapy, radiotherapy, and targeted therapy, seem to be affected when ISG15 levels are deregulated, suggesting that ISG15 may be implicated in the response to cancer therapies." (PMID 37711589, 2023).
cancer (continued). "Thus, ISG15 clearly has double-edged functions in malignant cancers, and proper consideration must be given to assess risk-benefit prior to administering ISG15-targeted cancer therapy to cancer patients when available." (PMID 35159348, 2022). "Beyond its intracellular functions, a portion of free unconjugated ISG15 is also released into the extracellular environment during infections and diseases such as cancer." (PMID 41599106, 2026). "Our findings not only elucidate a novel ISG15-HMGCR regulatory axis in PDAC pathogenesis but also establish a nanotechnology-enabled strategy to disrupt cancer stemness through metabolic targeting." (PMID 41366470, 2025). "This is also the first study to report ISG15 mRNA level in circulating leucocytes as an independent prognostic factor in the cancer field." (PMID 40936712, 2025). "Increasing evidence suggests that ISG15 plays a critical role in cancer development and progression." (PMID 40126377, 2025). "Collectively, we conclude that the expression of ISG15 and immune checkpoint genes are generally positively correlated across pan-cancers." (PMID 40208307, 2025). "For instance, vaccine against ISG15 protein antigen, ISG15 gene knockdown, ISG15 targeting to potentiate anti-PD-1’s efficacy in pre-clinical cancer models showed some early promises." (PMID 40936712, 2025). "Given the reported involvement of ISG15 in various cancer types, we first assessed the alteration of ISG15 in pan-cancers." (PMID 40208307, 2025). "Together, these cancer studies highlight the need for studying the role of extracellular ISG15 in cancer." (PMID 40719862, 2025). "Constitutive overexpression of ISG15 represents a pathological condition that manifests as increased ISG15 in cancers." (PMID 39589832, 2025). "To explore the possible mechanisms for ISG15 overexpression in human cancer, we examined the genetic alteration of ISG15 across various tumors utilizing the TCGA database via the cBioPortal website." (PMID 40208307, 2025). "Understanding these processes highlights the importance of ISG15 in cellular responses to genotoxic stress and its potential implications in cancer biology and therapies, particularly in the context of BRCA1/2 deficiencies." (PMID 40103488, 2025). "25% of cancers have alteration in ISG15 where majority of cases have overexpression of ISG15, consistent with elevation of ISG15 expression in human cancer." (PMID 40208307, 2025). "Here, we have described the prognostic value of ISG15 in pan-cancer and reported its immunological relevance in various cancers." (PMID 40208307, 2025). "Strikingly, while ISG15 silencing or statin treatment alone partially attenuated cancer stem cell (CSC) generation (as assessed by sphere formation), dual targeting nearly abolished spheroid formation capacity, suggesting synthetic lethality." (PMID 41366470, 2025). "Taking together, we conclude that both mRNA and protein levels of ISG15 are significantly elevated in most cancer types examined in this study." (PMID 40208307, 2025). "ISG15 and the subsequent ISGylation process are known to play critical roles in immune cell function, and ISG15 expression in cancer cells has been found to inhibit proliferation and induce apoptosis." (PMID 40273985, 2025). "Taken together, these data establish extracellular ISG15 as a multifunctional cytokine with pleiotropic effects on immune cells and cancer cells in infectious and cancerous contexts." (PMID 40719862, 2025). "In this study, we employed numerous pan-cancer databases for the first time to perform a pan-cancer analysis on ISG15 together with validations." (PMID 40208307, 2025). "Conversely, ISG15-mediated acceleration of replication forks was recently shown to increase replication stress and chromosomal instability in cancer cells, highlighting the potentially dual effects of ISG15 on DNA replication." (PMID 41188872, 2025).
cancer (continued). "One of the top genes detected more often in ultra-depth sequencing is ISG15, a ubiquitin-like protein involved in chemotactic and cancer-promoting signaling." (PMID 40530332, 2025). "ISG15, an interferon-stimulated gene involved in immune pathways, plays an immunoregulatory role in tumors and serves as a potential biomarker for cancer progression." (PMID 41160379, 2025). "We noticed that the level of Isg15, which plays an important role in cancer, was upregulated in HCC tumors from HFD‐fed mice than in those from NCD‐fed mice." (PMID 40126377, 2025). "By integrating multiomics data from TCGA, GEO, and clinical cohorts, we found that ISG15 is significantly overexpressed in multiple cancers and generally correlates with poor prognosis." (PMID 40208307, 2025). "ISG15 is considered a key regulatory factor in maintaining protein homeostasis and participates in the regulation of cancer and immune diseases." (PMID 40208307, 2025). "This study comprehensively evaluates ISG15 as a prognostic biomarker and predictor of immunotherapy response through pan-cancer bioinformatics analysis and experimental validation." (PMID 40208307, 2025). "In high-grade serous ovarian cancer (HGSOC), ISG15 enhances exocytosis and secretion of small extracellular vesicles (sEVs), promoting migration and invasion of cancer cells." (PMID 40103488, 2025). "ISG15’s key involvement in immune defense system has gained research interest in developing it as a target for cancer immunotherapy." (PMID 40936712, 2025). "Surprisingly, we found that ISG15 was lost in over 20% of cases across 21 out of the 31 human cancer types, while ISG15 was gained in over 20% of cases across 8 of 31 cancer types." (PMID 40208307, 2025). "ISG15 is also involved in cancer cell migration by binding to and activating the Rho GTPase family member Rac1, and regulating traditional EMT (epithelial–mesenchymal transition) signaling among others." (PMID 40208307, 2025). "Overall, ISG15 has been proved to regulate cancer progression and metastasis in various ways; thus, the regulatory role and prognostic predictive value of ISG15 in pan-cancers are apparent." (PMID 40208307, 2025). "Next, we validated the prognostic value of ISG15 using the Kaplan–Meier plotter, which encompasses meta-microarray transcriptional data and clinical outcomes across many human cancer types." (PMID 40208307, 2025). "In this review, we will summarize the novel roles of ISG15 in multiple cancer-related phenotypes, including apoptosis, autophagy, immune escape, metabolic reprogramming, cancer stem cells (CSCs) maintenance, and DNA damage response (DDR) resistance." (PMID 41193953, 2025). "Here, we aimed to reveal the clinical significance of ISG15 in PC and its regulatory mechanism in cancer progression and resistance to therapy." (PMID 38385083, 2024). "As one of the earliest IFN-stimulated genes (ISGs), ISG15 is abnormally up- or down-regulated in multiple types of cancer and infectious diseases." (PMID 39136821, 2024). "In recent studies, ISG15 has been demonstrated to play a significant role in the regulation of cell proliferation and metastasis in various human cancers." (PMID 38951255, 2024). "ISG15 and the enzymes responsible for catalysing ISGylation and deISGylation exhibit dysregulation in different cancer types, such as breast, ovarian, pancreatic, colorectal, glioma, and prostate cancers." (PMID 38400136, 2024). "ISG15 has been reported as a potential predictor for drug sensitivity 27, 41, and its impact on chemosensitivity has been shown in various cancers with conflicting roles 42-44." (PMID 38385083, 2024). "Moreover, interferon-stimulated gene 15 (ISG15) is associated with various types of cancer; however, its biological role in ccRCC remains unclear.This study aimed to explore the role of ISG15 in ccRCC progression.ISG15 expression was upregulated in ccRCC and associated with poor prognosis." (PMID 38951255, 2024).
cancer (continued). "Our results are consistent with previous reports demonstrating the upregulation of ISG15 in several types of cancer and suggest that ISG15 is directly or indirectly involved in cancer development." (PMID 38443596, 2024). "ISG15 expression during C. trachomatis infection was first examined in HeLa cells, a cancer cell line derived from the cervical epithelium." (PMID 39345209, 2024). "Recent studies have shown that targeting ISG15, using knockdown or a small molecule inhibitor, significantly inhibits cancer cell proliferation and induces apoptosis by increasing caspase‐3 and caspase‐9." (PMID 38939897, 2024). "ISG15 expression has been reported to be upregulated in several cancer cells, such as melanoma, breast, prostate, hepatocellular, lung and nasopharyngeal cancer." (PMID 38939897, 2024). "This review aims to contribute to future studies exploring the role of ISG15 in immune modulation and cancer therapy, potentially paving the way for the development of novel therapeutic interventions, vaccine development, and precision medicine." (PMID 38400136, 2024). "As such, the correlation between ISG15 levels and cancer activity is currently unclear and likely depends on the cellular and the tumoral context." (PMID 38939897, 2024). "Taken together, these data demonstrated that KPNA2 mediated cancer stem-like characteristics of ATC reinforced by ISG15 and ISGylation." (PMID 37501099, 2023). "Some proteins modified by ISG15 have been identified in malignant neoplasms, suggesting the functional relevance of ISGylation in cancer." (PMID 37711589, 2023). "In this review, we aim to further clarify the function of ISG15 and ISGylation in cancer, demonstrate the important relationship between ISG15/ISGylation and cancer, and emphasize new insights into the different roles of ISG15/ISGylation in cancer progression." (PMID 36771004, 2023). "Based on the possibility of ISG15 to dominate cancer stem cell-like characteristics in ATC, two scRNA-seq datasets (GSE148673 and GSE29265) were integrated for analysis." (PMID 37501099, 2023). "Future investigations are needed to identify those factors that, in combination with the upregulation of ISG15, are required to alter fitness and drug sensitivity of BRCA1/2-mutated cancer cells." (PMID 37783689, 2023). "The elevated expression of ISG15 is found to be consistent across all cancer stages, as well as CRC subtypes, and does not discriminate between males versus females." (PMID 36831577, 2023). "This review discusses the ISGylated proteins reported in malignant neoplasms that suggest the potential of ISG15 as a biomarker and therapeutic target in cancer." (PMID 37711589, 2023). "Protein ISGylation levels and the ISGylated protein types can affect the response to chemotherapeutic treatments; studies in more depth are required to understand the role of ISG15/ISGylation in cancer therapies." (PMID 37711589, 2023). "The ISG15 pathway has mostly been studied in the context of viral and bacterial infections and in cancer." (PMID 37025175, 2023). "EP3 showed a unique signature of interferon-stimulated genes IFIT1-3 (logFC >2.5), IFITM1-3 (logFC >0.6), and ISG15 (logFC = 2.5), previously characterized as markers of cancer stem cells (CSC)." (PMID 38328306, 2023). "For delineating the mechanism of ISG15 and ISGylation in modulate cancer stem cell-like characteristics, the physical interaction analysis was conducted to screen a range of potential substrates, including Karyopherin α2 (KPNA2)." (PMID 37501099, 2023). "Flow cytometry combined with immunofluorescence were used to verify the enrichment of ISG15 and ISGyaltion in cancer stem cells." (PMID 37501099, 2023). "The IDEGs (SLPI, IAPP, NPY, ISG15, PLA2G2A, and HLA-DMB) in the predictive PCa risk model constructed in the present study play an important regulatory role in cancer." (PMID 36774376, 2023).
cancer (continued). "There is growing evidence showing that both the free and conjugated ISG15 are involved in multiple key cellular processes, including autophagy, exosome secretion, DNA repair, immune regulation, and cancer occurrence and progression." (PMID 36771004, 2023). "In summary, we have demonstrated for the first time that ISG15 maintains cancer stem cell-like characteristics by inhibiting KPNA2 degradation through ISGylation in ATC." (PMID 37501099, 2023). "We analyzed and confirmed the binding of KPNA2 to ISG15 and its ISGylation by mass spectrometry and experiments, and further identified KPNA2 as the mediator of ISG15 in modulating the cancer stem-like characteristics of ATC." (PMID 37501099, 2023). "ISG15, the first discovered ubiquitin-like protein, was identified to contribute to cancer progression through regulating the ubiquitination." (PMID 36969077, 2023). "Altogether, these findings reveal that the IFNβ/ISG15 system controls fork stability in clinically relevant pathological contexts, increasing the fitness of BRCA1/2-deficient cancer cells and affecting the drug response." (PMID 37783689, 2023). "In recent years, several studies have shown that both ISG15 and its covalently bound form play an important role in various cancers and therapeutic interventions." (PMID 36771004, 2023). "Further through overexpression of ISGylation and non-modification mutant, it was found that ISGylation was the core element for ISG15 mediated regulation of cancer stem-like characteristics." (PMID 37501099, 2023). "We found that inhibition of ISG15 blocked the cancer stem-like characteristics of ATC cells by experiments indeed, and significantly impeded ATC growth and metastasis in xenografted mouse and zebrafish models." (PMID 37501099, 2023). "ISG15 and ISGylation conjugating enzymes are frequently elevated in human malignant tumors, whereas some studies suggest a tumor-suppressive role of ISGylation in certain cancer cell lines, such as hepatocellular carcinoma and lung cancer." (PMID 38036512, 2023). "Taken together, our results indicated the critical roles of ISG15 and ISGylation in the maintaining cancer stem cell-like characteristics." (PMID 37501099, 2023). "Among the MUC1-induced IRDS genes, we identified ISG15, which is overexpressed in human cancers and couples chronic inflammation with DNA damage resistance." (PMID 36445328, 2023). "ISG15 is upregulated in diverse cancers by unclear mechanisms and is of potential importance for their responsiveness to genotoxic agents." (PMID 35681561, 2022). "The effects of ISG15 knockdown or induction were investigated for cancer stem cell (CSC) characteristics and for drug sensitivity in unique in vitro models of SFT." (PMID 35864381, 2022). "Further investigation on the functions of ISGylation/free ISG15 should be taken into consideration to assess risks and benefits prior to administering ISG15-targeted cancer therapy to patients when available." (PMID 35159348, 2022). "Similar to cancer and neurodegenerative disease models, ISG15 and ISGylation exert antiviral responses by inhibiting or promoting protein degradation." (PMID 35159348, 2022). "Taken together, the upregulation of BATF2 and the downregulation of both ISG15 and MT2A, as reported here in blood samples from children with ASD, suggesting a reduced risk of cancer." (PMID 36077244, 2022). "Our results demonstrate that MUC1-C in a complex with STAT1 and IRF1 constitutively activates ISG15 transcription, in support of MUC1-C involvement in integrating chronic activation of the type I IFN pathway with induction of ISG15 expression in cancer cells." (PMID 35681561, 2022). "The microarray data from the OncomineTM cancer Profiling Database reveal that ISG15 gene expression is elevated in various human malignancies such as breast, colon, tongue, and ovarian, among numerous others, compared to their normal counterparts." (PMID 35159348, 2022).